CCL4 (C-C motif chemokine ligand 4)
Diseases named in the same sentence as CCL4 in open-access papers (continued):
Sharing a sentence is not in itself a finding about the gene and the disease.
glioblastoma (8 papers, 2021 to 2025). The most malignant astrocytic tumor (WHO grade IV). "For example, CCL4 can help to recruit cytolytic CCR5+ T cells in esophageal squamous cell carcinoma, but the CCL4–CCR5 interaction can enhance the invasion ability of glioblastoma in vitro." (PMID 34771532, 2021). "CED of these recombinant cytokines in immunocompetent glioblastoma C57BL/6J mice nominated APOA1, IL-1B, and CCL4 as candidates that could increase immune cell infiltration and necrosis in the intracranial TIME." (PMID 40161763, 2025). "However, the Wnt/β-catenin pathway does not affect CCL4 gene expression in glioblastoma multiforme (GBM) cells, suggesting that CCL4 is not involved in β-catenin-promoted T-cell exclusion in the GBM microenvironment." (PMID 36231010, 2022).
injury (8 papers, 2017 to 2025). Damage inflicted on the body as the direct or indirect result of an external force, with or without disruption of structural continuity. "Treatment with an aqueous extract of STR significantly improved liver injury caused by CCL4, suggesting that STR exerts a significant protective effect on CCL4-induced acute liver injury." (PMID 36557783, 2022). "The alginate-microencapsulated HepLPC spheroids significantly improved the survival rate of mice with CCL4-induced liver injury." (PMID 34858956, 2021). "A noteworthy study concluded that microRNA-217–targeting NAT2 restrains proliferation and promotes apoptosis and autophagy in rat models of CCL4-induced liver injury." (PMID 34867333, 2021). "Food and water intake analyses showed that cADMSC injection accelerated recovery relative to CCL4-induced acute liver injury dogs." (PMID 30362962, 2018). "As elevated inflammatory cytokines are associated with fibrogenesis, we assessed the impact of TNF-α inhibition on ERG expression and SMAD3 activity by co-administration of the TNF-α antagonist etanercept in an acute CCL4-induced liver injury." (PMID 29026072, 2017). "In this study, we provide data that support a protective effect of the aqueous extract of STR in CCL4-induced liver injury, which may effectively alleviate CCL4-induced acute liver injury in mice." (PMID 36557783, 2022).
osteosarcoma (8 papers, 2018 to 2024). A usually aggressive malignant bone-forming mesenchymal neoplasm, predominantly affecting adolescents and young adults. "CCL4 has also been found to inhibit normal osteoblast function, increase osteoclast activity and stimulate bone destruction, but its effect in osteosarcoma is unclear." (PMID 34884541, 2021). "Levels of CCL4 expression were higher in osteosarcoma tissue than in normal bone tissue, and significant associations were observed with clinical disease stages." (PMID 34884541, 2021). "Further analyses revealed that miR-3927-3p expression was downregulated in osteosarcoma tissues and was negatively correlated with CCL4 expression." (PMID 34884541, 2021). "CCL4 regulates integrin αvβ3 expression and migratory activities in osteosarcoma cells via the FAK/AKT signaling pathway." (PMID 34884541, 2021). "Analysis of GEO Dataset osteosarcoma tissue samples revealed increased levels of CCL4 compared with levels in primary osteoblasts, especially in lung metastatic osteosarcoma tissue." (PMID 34884541, 2021). "When the osteosarcoma cell lines were treated with different concentrations of CCL4, cell migration ability was increased 2-fold." (PMID 34884541, 2021). "Significant positive correlations were found between CCL4 expression and integrin αv and β3 in clinical osteosarcoma tissues." (PMID 34884541, 2021). "Here, our use of MVC to block the function of the CCL4/CCR5 axis successfully inhibited integrin αvβ3 expression as well as the migration of osteosarcoma cells, indicating that MVC has therapeutic efficacy in osteosarcoma metastasis." (PMID 34884541, 2021). "This study found high levels of CCL4 expression in clinical osteosarcoma tissue samples that correlated with clinical disease stages as well as the lung metastatic properties of this disease." (PMID 34884541, 2021). "It was found that CCL4 affects integrin αvβ3 expression and osteosarcoma cell migration, so the study sought to determine which signaling pathways underlie these activities." (PMID 34884541, 2021). "Analysis of mRNA expression in human osteosarcoma tissue identified upregulated levels of CCL4, integrin αv and β3 expression." (PMID 34884541, 2021). "Additionally, CCL4 facilitates the migration of osteosarcoma cells by activating signaling pathways such as focal adhesion kinase (FAK), protein kinase B (AKT), and hypoxia-inducible factor 1 subunit alpha (HIF-1α)." (PMID 39364412, 2024). "IHC staining and qPCR were performed to detect levels of CCL4 in osteosarcoma tissue." (PMID 34884541, 2021). "Importantly, the expression of both CCL4 and integrin αvβ3 correlated positively with osteosarcoma clinical stages and lung metastasis." (PMID 34884541, 2021). "In this study, our investigation into whether CCL4 affects osteosarcoma cell migration found that CCL4 promotes integrin αvβ3 expression by downregulating miR-3927-3p through the CCR5 and FAK/AKT/HIF-1α signaling pathway." (PMID 34884541, 2021). "CCL4 appears to be a new molecular therapeutic target in osteosarcoma metastasis." (PMID 34884541, 2021). "This study therefore examined whether FAK and AKT signaling is involved in CCL4-mediated osteosarcoma cell migration." (PMID 34884541, 2021). "Similarly, an analysis of records from the Gene Expression Omnibus (GEO) dataset showed that CCL4 was upregulated in human osteosarcoma tissue." (PMID 34884541, 2021). "This study is the first to investigate whether CCL4 has any direct effect in osteosarcoma." (PMID 34884541, 2021). "In osteosarcoma, FOXO1 acts as an inhibitory molecule in the WNT signalling pathway, promoting the upregulation of CCL4 expression." (PMID 38899748, 2024). "More interesting, we found many immune-related genes (including CCL3, CCL4, CCL4L2, and CXCL5) enriched in the thrombus samples of osteosarcoma, which indicates that multiple genes involved in immunological pathways may be activated concordantly." (PMID 37244923, 2023).
osteosarcoma (continued). "Notably, the local expression of CCL4 in tumor lesions was negatively correlated with the expression of NPTX2 in the TCGA datasets and in osteosarcoma patient samples." (PMID 34258887, 2021). "CCR5 receptor, that binds CCL3, CCL4, CCL5 and CCL8, is also involved in TAMs recruitment and plays a role in guiding invasion and metastasis of breast, cervical, lung, multiple myeloma, osteosarcoma, pancreatic, and prostate malignancies." (PMID 30591657, 2018). "First, the expression of CCR1 that binds to 6 ligands (CCL3, CCL4, CCL5, CCL7, CCL16, CCL23) has been shown to correlate with metastases in lung, prostate, cervical and hepatocellular carcinoma, multiple myeloma, T-cell leukaemia, and osteosarcoma." (PMID 30591657, 2018). "Treating osteosarcoma cells with CCR5, FAK, AKT or HIF-1α inhibitors reversed CCL4-mediated inhibition of miR-3927-3p expression, which suggests that CCL4 may increase integrin αvβ3 expression and cell migration by inhibiting miR-3927-3p synthesis via CCR5 and FAK/AKT/HIF-1α signaling." (PMID 34884541, 2021). "According to the evidence, CCL4 promotes integrin αvβ3 expression through the CCR5 receptor and then activates the FAK/AKT/HIF-1α signaling pathway, which subsequently inhibits miR-3927-3p expression and promotes integrin αvβ3 expression, as well as osteosarcoma cell migration." (PMID 34884541, 2021). "Furthermore, the two CD8 + cytotoxic clusters demonstrated upregulation of NKG7, GZMB, GZMH, GZMK, CCL3, CCL4, and CCL5, suggesting that chemotherapy amplified the cytotoxic function of CD8 + T cells, potentially enhancing their antitumor activity within the osteosarcoma tumor microenvironment." (PMID 39033089, 2024).
ZIKV infection (8 papers, 2017 to 2022). "ZIKV infection increases the levels of a series of cytokines (IL-1α, IL-6, IL-9, IL-10, IL-12p70, and IFN-γ) and chemokines (CCL2, CCL3, CCL4, CCL5, CCL11, and CXCL1) in mouse brain." (PMID 34399779, 2021). "Increased serum concentrations of both CXCL (CXCL8 and CXCL10) and CCL chemokines (CCL2, CCL3, CCL4, CCL5, and CCL11) were found in acute ZIKV infection." (PMID 29768624, 2018). "Moreover, ZIKV infection induced an increase in the chemokines CCL3, CXCL9, and CXCL8, while CCL4 and CXCL11 were significantly decreased." (PMID 33430059, 2021). "Acutely infected cells produced high levels of pro-inflammatory chemokines, including CCL2, CCL3, CCL4, CCL5 and CXCL8, which could contribute to CNS inflammation during ZIKV infection in vivo by promoting the recruitment of various leukocytes into the CNS." (PMID 32375993, 2020).
gastric cancer (7 papers, 2007 to 2024). A primary or metastatic malignant neoplasm involving the stomach. "Some of these chemokines and receptors, such as CXCL13, CCL4, CCL5, CCR2, CXCR3, and CXCR4, have been experimentally confirmed to be associated with the pathogenesis or prognosis of gastric cancer or other malignancies." (PMID 32685487, 2020).
multiple myeloma (7 papers, 2011 to 2025). "Studies have shown that CCL-3 and CCL-4 are predominant factors responsible for the enhancement of bone resorption in multiple myeloma and play a causal role in the development of lytic bone lesions in vivo." (PMID 30305140, 2018). "CCL3 and CCL4 expression has been detected in various B cell-related tumors, including multiple myeloma and chronic lymphocytic leukemia (CLL)." (PMID 28036258, 2017). "The magnitude of this effect was considerable with the most marked effects seen for CCL4 (CCR4 ligand) and CXCL9 (CXCR3 ligand), which were increased by 4 and 6 fold respectively in the bone marrow of patients with myeloma compared to controls." (PMID 28389623, 2017). "The most marked effects were seen for CCL4 and CXCL9 which were increased by 4 and 6 fold respectively in the bone marrow of patients with myeloma." (PMID 28389623, 2017). "Additionally, accumulating evidence indicates that ATM drives the BM-mediated resistance to chemotherapy in other hematological malignancies, such as multiple myeloma and acute lymphoblastic leukemia via upregulation of cytokines such as IL-6 or CCL3, CCL4, and GDF15." (PMID 36259537, 2022).
oral cancer (7 papers, 2017 to 2023). "In order to determine the mechanisms underlying CCL4-mediated angiogenesis of oral cancer, we treated OSCC cells with CCL4 for 120 min and observed time-dependent increases in STAT3 phosphorylation." (PMID 35884919, 2022). "A recent investigation showed that smoking along with CCL4 gene polymorphisms can increase risk of oral cancer." (PMID 32961854, 2020). "Similar to CCL5, CCL4 has analogous role in cancer progression; CCL4 enhances susceptibility to oral cancer." (PMID 32961854, 2020). "Our previous study demonstrated the involvement of CCL4 gene polymorphisms in oral cancer development." (PMID 29599774, 2018). "In our study, the synergistic effect of environmental factor (betel quid and smoking) and CCL4 gene SNPs (rs1634507, rs10491121, and rs1719153) on the risk of oral cancer are well demonstrated." (PMID 28404909, 2017). "The current study analyzed relationships between SNPs rs1634507, rs10491121, and rs1719153 of the CCL4 gene and the risk of oral cancer." (PMID 28404909, 2017). "For the genotypic frequencies of the SNPs, only CCL4 rs10491121 showed significant associations with clinical pathological variables in male oral cancer patients." (PMID 28404909, 2017). "We evaluated impacts of different haplotype combinations of 2 CCL4 SNPs (rs1634507, rs10491121) to the risk of oral cancer and eventually found that the GG haplotype showed a high risk for OSCC." (PMID 28404909, 2017). "We found that the T/T homozygotes of CCL4 rs1634507 G/T polymorphism and the GG haplotype of 2 CCL4 SNPs (rs1634507 and rs10491121) combined were associated with oral-cancer susceptibility." (PMID 28404909, 2017). "People with T/T homozygotes of CCL4 rs1634507 G/T polymorphism had a 1.479-fold (95% CI: 1.073–2.040; P = 0.017) significantly higher risk of developing oral cancer compared to those with G/G homozygotes after adjusting confound factors." (PMID 28404909, 2017). "Among smoker people with GT or TT genotype of CCL4 rs1634507 polymorphism combined with betel nut chewing had a 17.563-fold (95% CI: 11.856-26.018) increased risk to develop oral cancer compared with those with G/G homozygotes." (PMID 28404909, 2017). "As mentioned, smoking and betel nut chewing combination with CCL4 polymorphism can increased risk to rapid progress oral cancer; thus, a more active health education is needed in those patients with a higher CCL4L polymorphism." (PMID 28404909, 2017). "CCL4 polymorphisms may increase susceptibility to oral cancer, as serum levels of CCL4 have been observed to be considerably more significant in patients with head and neck squamous cell carcinoma than in controls." (PMID 37373025, 2023). "Serum concentrations of CCL4 have been found to be significantly higher in patients with head and neck squamous cell carcinoma compared with controls, and we have previously reported that CCL4 polymorphisms may enhance susceptibility to oral cancer." (PMID 29599774, 2018). "We found that participants with T/T homozygotes of CCL4 rs1634507 G/T polymorphism (OR: 1.479; 95% CI: 1.073–2.040; P = 0.017) were significantly associated with increased oral cancer risk compared to those with G/G homozygotes after adjusting confound factors." (PMID 28404909, 2017). "In conclusion, our results suggest that T allele of CCL4 rs1634507 G/T polymorphism may be associated with the susceptibility to oral cancer." (PMID 28404909, 2017). "Finally, patients with oral cancer who had A/G heterozygotes of CCL4 rs10491121 A/G polymorphism showed a lower risk for an advanced tumor size (> T2) (p=0.046), compared to those patients with AA homozygotes." (PMID 28404909, 2017). "In this study, we first investigated whether polymorphisms within the CCL4 gene played a significant role in the development of oral cancer." (PMID 28404909, 2017).
oral cancer (continued). "However, we also found that A/G genotype CCL4 rs10491121 polymorphism and GG haplotype combinations of CCL4 rs1634507/rs10491121 polymorphisms represented a protective factor for oral cancer development and progression." (PMID 28404909, 2017). "Consequently, enhance the risk of oral cancer with T allele of CCL4 rs1634507 polymorphisms." (PMID 28404909, 2017). "Gene-environment interactions of CCL4 polymorphisms might influence oral-cancer susceptibility." (PMID 28404909, 2017). "The CCL4 rs10491121 gene polymorphism may be a protective factor against oral cancer progression." (PMID 28404909, 2017). "CCL4 treatment of oral cancer cells upregulated Angpt2 expression and stimulated mitogen-activated protein kinase kinase (MEK), extracellular signal-regulated kinase 1/2 (ERK), and signal transducer and activator of transcription 3 (STAT3) phosphorylation." (PMID 35884919, 2022). "In this study, an analysis of records from The Cancer Genome Atlas (TCGA) database found higher CCL4 expression in oral cancer tissue than in normal healthy tissue." (PMID 35884919, 2022). "It has been shown that CCL4 stimulates VEGF-C expression by activating the JAK2/STAT3 signaling pathway, which is frequently linked with oral cancer cell proliferation, invasion, and angiogenesis." (PMID 32961854, 2020). "Correlation of clinical status with CCL4 expression [ranging from low (0–25%) to high (75–100%)] of 154 oral cancer patients." (PMID 29599774, 2018). "Another CCL4 haplotypes, T/A significantly decreased the risks for oral cancer by 0.118 fold (95% CI: 0.035-0.400)." (PMID 28404909, 2017). "Compared to the reference, CCL4 haplotypes, G/G, significantly increased the risks for oral cancer by 1.313 fold (95% CI: 1.110-1.553)." (PMID 28404909, 2017). "Also, AG or GG genotype of CCL4 rs10491121 polymorphism and AT or TT genotype of CCL4 rs1719153 polymorphism combined with betel nut chewing had a 20.247-fold (95% CI: 12.075-33.949) and a 15.476-fold (95% CI: 10.457-22.904) increased risk to progress oral cancer." (PMID 28404909, 2017). "CCL4 stimulation of oral cancer cells augmented JAK2 and STAT3 phosphorylation." (PMID 29599774, 2018). "Alleles with the highest distribution frequency for the rs1634507, rs10491121, and rs1719153 genes of CCL4 in both of our recruited male oral-cancer patients and healthy controls were respectively homozygous for G/G, heterozygous for A/G, and homozygous for A/A." (PMID 28404909, 2017). "Among 1420 smokers, CCL4 polymorphisms carriers with the betel-nut chewing habit had a 15.476–20.247-fold greater risk of having oral cancer compared to CCL4 wild-type (WT) carriers without the betel-nut chewing habit." (PMID 28404909, 2017). "These study findings suggest that CCL4 plays an important role in the oral cancer progression." (PMID 28404909, 2017). "Therefore, we thought that CCL4 might have an important role in oral cancer progression and lymph node metastasis." (PMID 29599774, 2018). "Transfection of oral cancer cells with MEK, ERK, and STAT3 inhibitors and their small interfering RNAs inhibited CCL4-induced promotion of Angpt2 expression and angiogenesis." (PMID 35884919, 2022). "We found that CCL4 increased VEGF-C expression and promoted lymphangiogenesis in oral cancer cells in vitro and in vivo." (PMID 29599774, 2018).
ovarian carcinoma (7 papers, 2020 to 2025). A malignant neoplasm originating from the surface ovarian epithelium. "We found that CCL2 and CCL4 were commonly expressed in several ovarian cancer cell lines, a patient-derived tumor cell line and patient serum samples in vitro." (PMID 41424784, 2025). "CCL4 has been reported to be involved in the metastasis, angiogenesis, and leukocyte trafficking of many tumor subtypes, including ovarian cancer." (PMID 36131935, 2022). "However, CCL8 in addition to CCL4/5 has been reported to induce the homing of CCR1/5 + intraepithelial CD8 T cells in ovarian cancer, thereby favouring improved response." (PMID 40280979, 2025). "However, levels of CCL2 and CCL4 were significantly increased in patients with ovarian cancer compared to healthy donors." (PMID 41424784, 2025). "Ovarian cancer chemokine landscape profiling revealed chemokines such as CCL2, CCL4, CCL5, CXCL10, and CXCL12 as potential candidates in ovarian cancer." (PMID 41424784, 2025). "In a cultured cell line derived from the ascites of a patient with platinum resistant ovarian cancer (ET2), elevated levels of CCL2, CCL3, CCL4, CCL5, CXCL1, CXCL8 and CXCL10 were detected in the cultured media." (PMID 41424784, 2025). "similarly found a correlation between increased intratumoral CCL4 and CD8+ T cells in ovarian cancer." (PMID 36131935, 2022). "Additionally, in ovarian cancer (OC) patients, circulating CXCL1, CCL4, and CCL20 are elevated in serum specimens, which are associated with shorter recurrence-free survival (RFS) and OS." (PMID 36612163, 2022). "Chemotherapy with paclitaxel or carboplatin may generate debris in ID8 ovarian cancer cells which triggers macrophage production of the proinflammatory cytokines TNF-α, MIP-2/CXCL2, MIP-1β/CCL4, CCL2/MCP-1, as well as sICAM-1/CD54 and G-CSF." (PMID 33194645, 2020). "Using female healthy donors with no history of ovarian cancer, we were also able to detect levels of CCL2, CCL4, CCL5, CXCL10 and CXCL12." (PMID 41424784, 2025).